NLRP3 (NLR family pyrin domain containing 3)
Diseases named in the same sentence as NLRP3 in open-access papers (continued):
Sharing a sentence is not in itself a finding about the gene and the disease.
Obesity (continued). "When categorizing participants based on their body mass index, it is observed that the NLRP3 gene response is more pronounced in individuals with normal weight compared to those with obesity." (PMID 40761804, 2025). "Studies have demonstrated that NLRP3 knockout in mice can prevent obesity-induced inflammasome activation in adipose tissue and the liver, enhancing insulin signaling." (PMID 40718836, 2025). "In AT macrophages, a second pathway involving NLR family pyrin domain-containing 3 (NLRP3) regulates caspase-1 activation, leading to the release of IL-1 and IL-8, which are crucial in the development of obesity-related complications." (PMID 41007770, 2025). "Inhibits palmitate-induced activation of NLRP3 inflammasome and ameliorates obesity-related inflammation by inducing macrophage autophagy." (PMID 40433411, 2025). "Emerging evidence suggests that ceramide activation plays a crucial role in triggering caspase-1 activation and IL-1β production via the NLRP3 inflammasome pathway, contributing to pathological conditions like obesity, podocyte damage, and acute lung injury." (PMID 40002829, 2025). "Our study aimed to elucidate the intricate involvement of the NLRP3 inflammasome pathway in the context of both obesity and COVID-19." (PMID 40004007, 2025). "To corroborate the role of NLRP3 inflammasome in the onset of HFD‐induced obesity, we performed experiments in mice with NLRP3 gene deletion." (PMID 39287080, 2025). "In the context of chronic caloric surplus-induced obesity, elevated levels of DAMPs, including glucose, fatty acids, and reactive lipids, also provoke NLRP3 inflammasome activation." (PMID 40433411, 2025). "The activation of the NLRP3 inflammasome has been identified as a significant factor in obesity‐induced inflammation and insulin resistance." (PMID 40589337, 2025). "Anti-obesity measures such as caloric restriction and exercise were shown to lower levels of adipose NLRP3 and suppress inflammation." (PMID 40430076, 2025). "Elevated IL-1β and IL-18 levels are consistently observed in the adipose tissue and serum of individuals with obesity and insulin resistance, and higher NLRP3 expression in visceral adipose tissue correlates with the severity of insulin resistance." (PMID 40943225, 2025). "A compelling body of evidence has delineated a mechanistic link between obesity and AF, with a key role attributed to NLRP3 inflammasome activation within the atrial myocardium." (PMID 40649732, 2025). "In obesity, chronic stimuli like free fatty acids and oxidized lipoproteins maintain NLRP3 activation, increasing IL-1β and IL-18 levels." (PMID 40004007, 2025). "In obesity, NLRP3 detects danger signals, contributing to insulin resistance and glucose dysregulation through adipose tissue inflammation and a pro-inflammatory T-cell shift." (PMID 40227195, 2025). "Increased activity of the NACHT, LRR and PYD domains-containing protein 3 (NLRP3) inflammasome–IL-1β pathway is observed in obesity and contributes to the development of type 2 diabetes and its complications." (PMID 39496966, 2025). "We found that individuals with obesity and COVID-19 exhibited heightened activation of part of the NLRP3 inflammasome pathway, as evidenced by elevated levels of key protein structures such as ASC and CASP-1." (PMID 40004007, 2025). "The NLRP3 inflammasome contributes to obesity-induced inflammation, and ablation of NLRP3 in mice prevents obesity-induced inflammasome activation in fat depots." (PMID 40216765, 2025). "NLRP3, IL‐1β, and ILC3 cells also seem to play a role in obesity‐associated asthma and contribute to airway hyperresponsiveness associated with obesity‐associated asthma." (PMID 39800672, 2025). "The interplay between iron metabolism and NLRP3 inflammasome signaling represents a critical but poorly understood axis in the pathophysiology of obesity and type 2 diabetes (T2D)." (PMID 40943225, 2025).
Obesity (continued). "Inhibiting the NLRP3 inflammasome has been observed to enhance metabolic health and lifespan in HFD‐induced obesity models, positioning NLRP3 as a promising therapeutic target at the intersection of metabolic dysregulation, neuroinflammation, and AD pathology." (PMID 40589337, 2025). "In summary, this research emphasizes the vital involvement of the mt-dsRNA-PKR axis in NLRP3 inflammasome-mediated NP cell pyroptosis during obesity induced IVDD." (PMID 41163024, 2025). "While the previous literature has explored NLRP3 inflammasome markers in COVID-19 patients, there is a gap in understanding these markers within the populations with obesity, necessitating further investigation for direct comparative analyses." (PMID 40004007, 2025). "Recent studies have explored the connection between Th2 response cytokines and NLRP3 in human and mouse models of obesity-induced asthma." (PMID 41007770, 2025). "Moreover, our findings demonstrate that the observed disparities in NLRP3 inflammasome activation between the groups may stem from a multitude of factors, including the presence of comorbidities, especially obesity itself, and the duration of underlying illnesses." (PMID 40004007, 2025). "Endoplasmic reticulum (ER) stress, a process activated in obesity, triggers the activation of NLRP3 inflammasome through the generation of ROS and potassium efflux." (PMID 40433411, 2025). "Chamomile lactone, an NLRP3 inflammasome inhibitor, shows potential as a therapeutic agent for reducing obesity-induced insulin resistance." (PMID 40433411, 2025). "Obesity-induced inflammation is also inextricably linked to the activation and assembly of the NOD-like receptor protein 3 (NLRP3) inflammasome through the sensing of various metabolic DAMPs (e.g., palmitic acid, cholesterol crystals)." (PMID 39532538, 2025). "Taken together, our findings show that IL-9 signaling is protective against obesity and insulin resistance and that IL-9 mediates its effects on glucose homeostasis and inflammation by inhibiting the NLRP3 inflammasome." (PMID 40962954, 2025). "Studies in both humans and animal models consistently show a strong correlation between obesity, insulin resistance, and increased NLRP3 expression in adipose tissue." (PMID 40648980, 2025). "Wheat germ agglutinin staining showed that NLRP3 deletion attenuated the increase in cardiomyocyte cross‐sectional area due to chronic obesity stimuli." (PMID 39604027, 2024). "Impeding NLRP3 inflammasome significantly improved obesity‐induced cardiac remodeling and cardiac systolic and diastolic dysfunction." (PMID 39604027, 2024). "Previous studies already showed evidence of increased NLRP3 inflammasome activation in mice in relation to obesity." (PMID 39696610, 2024). "The impact of NLRP3 inflammasome activation in obesity-induced insulin resistance and DMII is profound." (PMID 39301197, 2024). "Previously, we showed that NLRP3 inflammasome activation in atrial tissue is involved in AF pathogenesis and mediates atrial arrhythmogenesis in the context of obesity or chronic kidney disease." (PMID 38247800, 2024). "Lipid-lowering treatment has the potential to alleviate obesity-induced airway hyperresponsiveness and lung fibrosis by inhibiting the NLRP3 inflammasome, RAS and cholecystokinin activity." (PMID 38762465, 2024). "Our results suggest that mitochondrial ROS‐mediated TXNIP/NLRP3 inflammasome activation in cardiomyocytes plays a critical role in the pathogenesis of obesity cardiomyopathy." (PMID 39604027, 2024). "The importance of NLRP3 in obesity and metabolic inflammation has been further demonstrated in a preclinical study where the ablation of NLRP3 improved obesity-related inflammation and metabolic functions." (PMID 38672492, 2024). "In this study, we demonstrate that inhibition of NLRP3 inflammasome activity by NLRP3 deletion or injection of MCC950 prevented obesity‐induced cardiac dysfunction, pathological cardiac remodeling, and excessive lipid accumulation." (PMID 39604027, 2024).
Obesity (continued). "Vandanmagsar and colleagues discovered that in a controlled animal model, the deletion of NLRP3 resulted in a reduction of obesity-triggered inflammasome activation within adipose tissues." (PMID 38532994, 2024). "In conclusion, these results indicate that MitoTEMPO alleviates obesity‐induced cardiac dysfunction and cardiac remodeling by inhibiting NLRP3 inflammasome activation." (PMID 39604027, 2024). "The NLRP inflammasome, with a particular focus on NLRP3, appears to occupy a pivotal role in the intricate interplay of obesity and asthma." (PMID 38562155, 2024). "Activation of NLRP3 inflammasome-related gene expression with IL-1β exaggerates the asthmatic episode in patients with obesity and asthma." (PMID 39065704, 2024). "In early obesity, leptin signalling regulates NLRP3 inflammasome activation that supports M1 macrophage infiltration." (PMID 38580672, 2024). "Several studies have demonstrated that targeting NLRP3 expression is a potential method for suppressing obesity-related inflammation." (PMID 39275140, 2024). "It’s worth noting that a human study found that exercise reduces plasma IL-18 levels in obese individuals, indirectly suggesting the inhibition of the NLRP3 pathway through exercise to improve obesity." (PMID 38681198, 2024). "This body of research demonstrates that exercise exerts inhibitory effects on NLRP3 inflammasome activation across various cell types to ameliorate obesity." (PMID 38681198, 2024). "NLRP3 is also thought to be involved in the process of white adipose tissue browning, a mechanism that is discussed to induce beneficial effects in obesity." (PMID 39275140, 2024). "The current study confirmed that mitochondrial ROS‐mediated TXNIP/NLRP3 inflammasome activation in cardiomyocytes plays a critical role in the pathogenesis of obesity cardiomyopathy." (PMID 39604027, 2024). "The relationship between elevated NLRP3 levels and obesity indicates that these cascade events occur as a result of extracellular matrix remodeling of visceral adipose tissues." (PMID 38945951, 2024). "NLR family, pyrin domain-containing 3 (NLRP3) contributes to obesity-induced inflammation through NLRP3-induced activation of microglial IL-1 receptor 1 (IL-1R1)." (PMID 38685031, 2024). "Obesity stimulates the production of NLRP3 in diabetic patients, and there is a strong correlation between obesity and increased NLRP3 expression in adipose tissue and IR." (PMID 39328924, 2024). "Targeted knockout of NLRP3 at the level of the VAT attenuates diet-induced obesity cognitive deficits, thus implicating a potential role for NLRP3/IL-1β signaling in brain-visceral adipose tissue interactions related to obesity." (PMID 38685031, 2024). "SWELL1 and key markers of inflammation (NLRP3, NLRP6, IL1B, IL18 and IL8) were also upregulated in VAT in obesity and T2D being significantly associated (P < 0.01) with PIEZO1 levels." (PMID 39707172, 2024). "To characterise the role of leptin in the modulation of NLRP3 inflammasome profile changes and subsequent macrophage activation in the ovary during obesity, we used two genetically obese db/db and ob/ob mice, DIO mice, and the leptin treated LEPT mice." (PMID 38580672, 2024). "Our findings shed light on the pathogenesis of obesity cardiomyopathy and suggest that interventions that inhibit NLRP3 inflammasome activity are effective strategies for obesity cardiomyopathy." (PMID 39604027, 2024). "Several studies have clarified the relationship between obesity-related inflammation and NLRP3 and the involvement of this relationship in various disease states." (PMID 38945951, 2024). "In the present experiment, we confirmed that during obesity progression, ovarian leptin signalling regulates NLRP3 inflammasome activation and the expression of genes regulating M1 macrophage infiltration." (PMID 38580672, 2024).
Obesity (continued). "Thornton and colleagues examined the effects of two NLRP3 inflammasome inhibitors (NT-0249 and NT-0796) on obesity-induced complications such as systemic inflammation and astrogliosis." (PMID 38732190, 2024). "NLRP3 (NLR family pyrin domain-containing 3) inflammasome is the best-known player related to obesity-induced inflammation." (PMID 39630946, 2024). "It is thought that activation of the NLRP3 inflammasome is central to the pathophysiology of obesity and insulin resistance." (PMID 38725443, 2024). "We have previously shown that activation of the ‘NLR family pyrin domain containing 3′ (NLRP3) inflammasome signaling enhances atrial arrhythmogenesis in various contexts, such as obesity, post-surgical procedures, and chronic kidney disease." (PMID 38247800, 2024). "Future work should evaluate differences in NLRP3 inflammasome proteins after mTBI based upon clusters of obesity and obesity-related medical conditions." (PMID 38702410, 2024). "Both OSA and obesity can induce systemic inflammation via hypoxia-inducible factor-1 and nuclear factor κB pathways, as well as the NLRP3 inflammasome." (PMID 39201638, 2024). "NLRP3 inflammasome inhibition by NLRP3 deletion or MCC950 prevented obesity‐induced cardiac systolic and diastolic dysfunction, myocardial hypertrophy and fibrosis, and excessive lipid accumulation in male mice." (PMID 39604027, 2024). "Excessive NLRP3 inflammasome activation contributes to obesity‐induced chronic low‐grade inflammation." (PMID 39425563, 2024). "The article titled “The NLRP3 Inflammasome Instigates Obesity-Induced Inflammation and Insulin Resistance”, was authored by Bolormaa Vandanmagsarin and published in NAT MED in 2011." (PMID 39717099, 2024). "Our study confirmed that NLRP3 inflammasome activation substantially contributed to obesity‐induced heart failure." (PMID 39604027, 2024). "Inhibition of NLRP3 inflammasome by NLRP3 deletion or MCC950 mitigates obesity‐induced cardiac dysfunction, cardiac remodeling, and excessive lipid accumulation." (PMID 39604027, 2024). "Obesity is a major risk factor and disease modifier in asthma, and studies in obese asthmatic mouse have revealed that AHR can be NLRP3-dependent." (PMID 39554494, 2024). "Further research will enhance understanding of the complex relationship between exercise and NLRP3 inflammasome, leading to more effective interventions for managing obesity-related diseases." (PMID 38681198, 2024). "Our prior research has established that the NLRP3 inflammasome plays a critical role in AF development in obesity or chronic kidney disease models, serving as a mechanistic link between these risk factors and increased AF risk." (PMID 38247800, 2024). "But there is no detailed discussion of the specific molecular pathways of how obesity triggers inflammation and insulin resistance through the NLRP3 inflammasome, and how these pathways affect the treatment of obesity and related metabolic diseases." (PMID 39717099, 2024). "In obesity the activation of the NLRP3 inflammasome promotes the recruitment and activation of macrophages in adipose tissue, which in turn stimulates T cell activation." (PMID 39590865, 2024). "In the HFD-induced obesity model, aerobic exercise effectively suppressed the activation of the NLRP3 inflammasome in the left ventricles, consequently reducing expressions of NLRP3, ASC, pro-caspase-1, and IL-1β in the myocardium." (PMID 37859981, 2023). "The NLRP3 inflammasome has the ability to sense obesity-induced danger signals, leading to cardiac remodeling." (PMID 37035745, 2023). "In T2D and obesity, FFAs are also necessary for the activation of the NLRP3 and the production of IL-1b." (PMID 37241737, 2023). "In conclusion, obesity and PCOS seem to be associated with upregulated expression of NLRP3 inflammasome components." (PMID 37446154, 2023). "Our results revealed that downregulation of OIP5‐AS1 can inhibit obesity‐induced myocardial pyroptosis via miR‐22/NLRP3 inflammasome axis." (PMID 37904706, 2023).
Obesity (continued). "One clear correlation exists between obesity, mitochondrial dysfunction, and activation of the NF-kB—NLRP3 pathway." (PMID 37372020, 2023). "As Nlrp3 KO in mice in most studies leads to improved AT inflammation and glycemia, NLRP3 inhibition in humans appears as a promising treatment option for obesity-induced IR and T2DM." (PMID 37239938, 2023). "The aim of this meta-analysis was to investigate the possible role of the NLRP3 inflammasome in obesity and polycystic ovarian syndrome (PCOS)." (PMID 37446154, 2023). "Especially, the accumulation of NLRP3 promoted obesity-related impairment of spermatogenesis and testosterone synthesis by triggering interleukin-1β (IL-1β) secretion." (PMID 37935689, 2023). "It was demonstrated that high-fat diet-induced obesity leads to NLRP3 inflammasome activation in adipose tissue and subsequently promotes systemic inflammation." (PMID 38068904, 2023). "We and others have shown that the NLRP3 inflammasome is a major mechanism that controls macrophage-derived inflammation in obesity." (PMID 37781916, 2023). "Additively, PQQ possesses pharmacological effects on mitigating NLRP3 inflammasome-mediated pyroptosis to block the progression of inflammatory disease such as diabetes and obesity." (PMID 37935689, 2023). "The NF-kB—NLRP3 inflammasome pathway can be activated by endogenous cytokines that increase during obesity and this activation is mediated by Toll-like receptors (TLRs)." (PMID 37372020, 2023). "Several studies have demonstrated that metabolic disorders, such as obesity, insulin resistance, and impaired glucose metabolism, can contribute to the activation of the NLRP3 inflammasome and subsequent neuroinflammation." (PMID 38068904, 2023). "By targeting GSDMD, MT inhibits the activation of NLRP3 inflammasome in adipose tissue of mice and inhibits pyroptosis to alleviate obesity." (PMID 37125240, 2023). "In the lungs of obesity-related asthma mice, the NLRP3-IL-1β pathway is activated to induce the expansion of lung IL-17+ILC3 cells, leading to neutrophilic inflammation." (PMID 38029078, 2023). "Further research is required to validate these findings and to elucidate the role of NLRP3 in obesity and PCOS." (PMID 37446154, 2023). "In mice, ablation of NLRP3 prevented the obesity-induced inflammasome activation in fat depots and liver together with enhanced insulin-signaling." (PMID 36817440, 2023). "NLRP3 inflammasome has also been reported to be activated under obesity conditions through a hypoxia-dependent mechanism." (PMID 37819510, 2023). "Oxidative stress and the resulting generation of ROS have also been proposed as the NLRP3 priming signal in the context of obesity." (PMID 37239938, 2023). "As obesity is a major determinant of NLRP3 expression, the results of these studies should be interpreted with extreme caution." (PMID 37446154, 2023). "In consistent with our findings, a 12-week strength and endurance combined training also significantly inhibited the activation of the NLRP3 signaling pathway that induced by obesity in children." (PMID 36817440, 2023). "For example, some danger signals related to obesity, such as palmitate, lipids, and ceramides, are involved in NLRP3 inflammasome activation." (PMID 38069047, 2023). "Obesity-mediated inflammation through the NLRP3 inflammasome appears to play an important role in MAFLD development." (PMID 36670488, 2023). "CY-09 has been reported to inhibit NLRP3 inflammasome activation in order to improve insulin resistance in obesity and non-alcoholic fatty liver disease." (PMID 36978970, 2023). "Nowadays, evidence is apparent that obesity-induced activation of inflammatory cytokines (e.g., NLRP3, IL-1β, IL-18) is a major culprit behind the adiposity-related metabolic complication." (PMID 37935689, 2023).